GLB1 (galactosidase beta 1)
Description:
[Isoform 1]: Cleaves beta-linked terminal galactosyl residues from gangliosides, glycoproteins, and glycosaminoglycans. [Isoform 2]: Has no beta-galactosidase catalytic activity, but plays functional roles in the formation of extracellular elastic fibers (elastogenesis) and in the development of connective tissue. Seems to be identical to the elastin-binding protein (EBP), a major component of the non-integrin cell surface receptor expressed on fibroblasts, smooth muscle cells, chondroblasts, leukocytes, and certain cancer cell types. In elastin producing cells, associates with tropoelastin intracellularly and functions as a recycling molecular chaperone which facilitates the secretions of tropoelastin and its assembly into elastic fibers.
Synonyms: ELNR1; EBP; MPS4B
Tractability: Small molecule: a structure with a bound ligand is known; a high-quality ligand is known; it belongs to a druggable protein family. Antibody: its Gene Ontology location is reachable by antibodies, with high confidence; UniProt predicts a signal peptide or a membrane-spanning region. PROTAC: ubiquitination databases record sites on it; its protein half-life has been measured; a small molecule that binds it is known.
Target class: Enzyme; Hydrolase
Gene: Protein-coding gene on chromosome 3 (32,996,609 to 33,097,202, reverse strand). Ensembl gene ENSG00000170266.
Subcellular location: Lysosome (Isoform 1); Cytoplasm, perinuclear region (Isoform 2)
Subcellular location (Human Protein Atlas): Vesicles; Golgi apparatus
Pathways (Reactome):
Disease: Defective NEU1 causes sialidosis; MPS IV - Morquio syndrome B (CS/DS degradation); MPS IV - Morquio syndrome B (Keratin metabolism)
Metabolism: CS/DS degradation; Glycosphingolipid catabolism; Keratan sulfate degradation
Immune System: Neutrophil degranulation
Metabolism of proteins: Sialic acid metabolism
Gene Ontology:
Molecular function: beta-galactosidase activity; protein binding; protein homodimerization activity; galactoside binding; hydrolase activity; hydrolase activity, hydrolyzing O-glycosyl compounds
Biological process: carbohydrate metabolic process; ganglioside catabolic process; glycoprotein catabolic process; keratan sulfate proteoglycan catabolic process; galactose catabolic process; response to cortisone; response to Thyroglobulin triiodothyronine
Cellular component: cytoplasm; extracellular exosome; lysosome; azurophil granule lumen; extracellular region; ficolin-1-rich granule lumen; lysosomal lumen; vacuole; perinuclear region of cytoplasm
Genetic constraint (gnomAD): Loss-of-function variants: 58 observed, 76.99 expected, observed/expected ratio (o/e) 0.75, 90% interval 0.61 to 0.94. The upper end of that interval is the gene's LOEUF score, 0.94, which puts it in group 3 of 6, group 1 being the genes least tolerant of losing a copy. Missense variants: 787 observed, 879.28 expected, observed/expected ratio (o/e) 0.9, 90% interval 0.84 to 0.95. Synonymous variants: 323 observed, 337.07 expected, observed/expected ratio (o/e) 0.96, 90% interval 0.87 to 1.05.
Gene-disease validity (ClinGen):
ClinGen rates the evidence that GLB1 causes each of these diseases.
GM1 gangliosidosis (autosomal recessive): Definitive. A rare lysosomal storage disorder characterized biochemically by deficient beta-galactosidase activity and clinically by a wide range of variable neurovisceral, ophthalmological and dysmorphic features.
mucopolysaccharidosis type 4B (autosomal recessive): Definitive. A rare autosomal recessive lysosomal storage disease caused by deficiency of the enzyme beta galactosidase.
Homologues: Orthologues: chimpanzee GLB1 (96% identical), macaque GLB1 (91% identical), dog GLB1 (80% identical), mouse Glb1 (73% identical), rat Glb1 (72% identical), pig GLB1 (71% identical), rabbit GLB1 (71% identical), guinea pig GLB1 (69% identical), tropical clawed frog glb1l (63% identical), zebrafish glb1 (61% identical), Drosophila melanogaster Ect3 (40% identical), Drosophila melanogaster Gal (37% identical), and 2 more. Paralogues in human: GLB1L (52% identical), GLB1L2 (35% identical), GLB1L3 (31% identical).
Diseases named in the same sentence as GLB1 in open-access papers:
GLB1 is named in the same sentence as 99 diseases in open-access papers, as found by Europe PMC text mining. Sharing a sentence is not in itself a finding about the gene and the disease. The quoted sentences say what the papers report.
GM1 gangliosidosis (64 papers, 2010 to 2026). "GM1 gangliosidosis is an autosomal recessive lysosomal storage disorder caused by pathogenic GLB1 variants that impair β-galactosidase activity, resulting in GM1 ganglioside accumulation." (PMID 41732653, 2026). "GM1 gangliosidosis is a lysosomal storage disease (LSD) caused by mutations in the β-galactosidase (Glb1) gene impeding its enzyme activity." (PMID 40270964, 2025). "We detected compound heterozygous mutations in GLB1 gene by WES in a Chinese family with GM1 gangliosidosis presenting with late-infantile form, in which c.1058_1059delinsAA is a novel mutation." (PMID 39902059, 2025). "A mutation in the GLB1 gene on chromosome 3p22.3 causes infantile GM1 gangliosidosis, also known as mono-sialo-tetra-hexosylganglioside, a rare autosomal recessive lysosomal storage disorder." (PMID 40170955, 2025). "Pathogenic variants in the GLB1 gene lead to two distinct clinical disorders: GM1 gangliosidosis and MPS IVB (Morquio B disease)." (PMID 41154677, 2025). "Mono-sialo-tetra-hexosylganglioside, also known as infantile GM1 gangliosidosis, is an autosomal recessive lysosomal storage disorder caused by a mutation in the GLB1 gene that stops the β-galactosidase enzyme from working." (PMID 40170955, 2025). "GM1 gangliosidosis is an autosomal recessive lysosomal storage disorder caused by mutations in the GLB1 gene, leading to a deficiency of acid β-galactosidase." (PMID 39902059, 2025). "In this study, we examined GLB1 mutations in two patients from a Chinese Han family with GM1 gangliosidosis." (PMID 39902059, 2025). "Differences in clinical score between Glb1-/- and Glb1+/+ mice towards the end of the experiment are likely caused by clinical alterations related to GM1 gangliosidosis, as this is consistent with the established onset of clinical symptoms in this mouse model." (PMID 40270964, 2025). "GM1 gangliosidosis, caused by biallelic variants in GLB1, results from deficiency of lysosomal β-galactosidase, the enzyme primarily responsible for degradation of GM1 ganglioside." (PMID 40766118, 2025). "Clinical exome sequencing revealed pathogenic heterozygous variants in GLB1, consistent with GLB1-related GM1 gangliosidosis." (PMID 39897471, 2025). "For example, GM1 gangliosidosis, caused by mutations in GLB1 leading to deficiencies in lysosomal-β-galactosidase, massively accumulates lysosomal GM1." (PMID 41227379, 2025). "Our study expands the GLB1 gene mutation spectrum of GM1 gangliosidosis, emphasizes the importance of WES in evaluating patients with undiagnosed genetic diseases, and provides a new basis for genetic counseling." (PMID 39902059, 2025). "GM1 gangliosidosis (GM1) is an ultra-rare lysosomal storage disease caused by pathogenic variants in galactosidase beta 1 (GLB1; NM_000404), primarily characterized by neurodegeneration, often in children." (PMID 38313286, 2024). "GM1 gangliosidosis is an ultra-rare inherited neurodegenerative lysosomal storage disorder caused by biallelic mutations in the GLB1 gene." (PMID 39371116, 2024). "GM1-gangliosidosis results from mutations in the β-galactosidase 1 (GLB1) gene, which, in turn, cause enzyme deficiency and accumulation of GM1-ganglioside in various tissues of patients, predominantly affecting the nervous system." (PMID 36835039, 2023). "In the Alaskan Husky, the causal variant associated with GM1 gangliosidosis was a 19 bp insertion (duplication) in exon 15 of the GLB1 gene." (PMID 38003185, 2023). "Several mouse models of GM1 gangliosidosis have been established by targeting the Glb1 gene, but it has been puzzling that a complete deficiency of Glb1 in mice does not cause such a severe phenotype as the human infantile form of GM1-gangliosidosis." (PMID 37972730, 2023). "Pathogenic variants in GLB1 are associated with GM1 gangliosidosis; however, the patient’s phenotype was milder than expected." (PMID 37291213, 2023).
GM1 gangliosidosis (continued). "GM1 gangliosidosis is a lysosomal storage disease (LSD) caused by mutations of the GLB1 gene, which encodes βGal-ase—the enzyme hydrolyzing GM1 into GM2." (PMID 37298512, 2023). "GLB1 - two heterozygous variants, one in exon 11 (c.1122T>G) and one in intron 1 (c.75+3_75+4 del) causing GM1 gangliosidosis, an autosomal recessive disorder with one variant classified as pathogenic and the other as uncertain significance." (PMID 37519562, 2023). "GM1 gangliosidosis is a degenerative neurosomatic lysosomal storage disorder attributed to variants in the GLB1 gene, which encodes the enzyme β-galactosidase." (PMID 38003185, 2023). "There are several ongoing phase I/II clinical trials for GM1 gangliosidosis, evaluating the safety and efficacy of adeno-associated virus-mediated GLB1 delivery by intravenous injections." (PMID 36009508, 2022). "GM1 gangliosidosis is a rare inborn error of metabolism caused by mutations in the galactosidase beta 1 (GLB1) gene leading to a deficiency in the lysosomal enzyme b-galactosidase." (PMID 35207493, 2022). "Deficient β-galactosidase activity in humans is linked to mutations of the GLB1 allele in the autosomal recessive syndromes GM1 gangliosidosis and Morquio B disease." (PMID 35967980, 2022). "A fusion protein of RTB and iduronidase (IDUA), the enzyme mutated in MPSI, or RTB and beta galactosidase 1 (GLB1), the enzyme mutated in GM1 gangliosidosis, were engineered and expressed in plants." (PMID 35745855, 2022). "GM1 gangliosidosis is a result of homozygous or compound heterozygous (biallelic) mutations in the GLB1 gene." (PMID 36003149, 2022). "GM1 gangliosidosis, a progressive neurodegenerative lysosomal storage disease, occurs in the Shiba Inu breed due to the GLB1:c.1649delC (p.P550Rfs*50) mutation." (PMID 35625088, 2022). "GM1 gangliosidosis is a progressive, neurosomatic, lysosomal storage disorder caused by mutations in the GLB1 gene encoding the enzyme β-galactosidase." (PMID 34539759, 2021). "The most recent β-gal mutant mouse generated using CRISPR/Cas9 is a knock-in model that introduces a human missense mutation in exon 14 of Glb1, described in a patient with late-infantile GM1 gangliosidosis." (PMID 34539759, 2021). "The missense Tyr270Asp variant in GLB1 is associated with GM1-gangliosidosis (rs376663785, VCV000284172.5) and was observed in three copies in the Ivanovo population." (PMID 34691145, 2021). "Biallelic GLB1 mutations are pathogenic for GM1 gangliosidosis, an AR LSD characterised by β-galactosidase deficiency and ganglioside substrate accumulation within lysosomes." (PMID 34149605, 2021). "GM1 gangliosidosis is an autosomal recessive disorder resulting in a deficiency of β-galactosidase due to the mutation of the GLB1 gene." (PMID 32961778, 2020). "GLB1 mutations are typically associated with a progressive neuronopathic condition spanning from infantile to juvenile and late onset GM1 gangliosidosis." (PMID 33266180, 2020). "It is worth noticing that variants on GLB1 can be associated either with MPS IVB or GM1 gangliosidosis." (PMID 33208168, 2020). "GM1 gangliosidosis is a rare genetic disorder caused by mutations in the GLB1 gene, which encodes lysosomal beta-galactosidase (β-gal)." (PMID 33045869, 2020). "GM1-gangliosidosis is a lysosomal storage disease belonging to the sphingolipidoses caused by β-galactosidase (Glb1) deficiency." (PMID 32252429, 2020). "GM1-gangliosidosis is caused by a reduced activity of β-galactosidase (Glb1), resulting in intralysosomal accumulations of GM1." (PMID 32252429, 2020). "The aim of this study was to reveal the pathogenic mechanisms of GM1-gangliosidosis in a new Glb1 knockout mouse model." (PMID 32252429, 2020). "Using CRISPR-Cas9, mutation W273L (position 274 in mice) was introduced into the GLB1 gene to generate a Morquio B model, while for GM1-gangliosidosis, a 20bp mutation was generated to remove the catalytic nucleophile of β-gal (β-gal-/-)." (PMID 31771289, 2019).
GM1 gangliosidosis (continued). "Allelic mutations of the GLB1 gene cause heterogeneous clinical phenotypes, such as GM1-gangliosidosis and Morquio B syndrome." (PMID 31771289, 2019). "Deficiency of β-galactosidase (GLB1) causes two clinically distinct phenotypes: GM1-gangliosidosis (OMIM 230500) and mucopolysaccharidosis type IVB (MPS IVB, Morquio B syndrome, OMIM 253010)." (PMID 31905715, 2019). "GLB1 mutations in GM1 gangliosidosis, HEXA mutations in Tay-Sachs disease, and HEXB mutations in Sandhoff disease were found in all, of which GLB1 c.622C>T (p.R208C) in P108 was a common mutation for patients with GM1 gangliosidosis." (PMID 29451896, 2018). "Pathogenic variants in GLB1 cause two different lysosomal storage disorders: GM1 gangliosidosis and mucopolysaccharidosis type IVB." (PMID 30187681, 2018). "Our study identified the first GLB1 mutation in North Africa in patients with unexpected brain-MRI outcomes extending the clinical spectrum of the GM1-gangliosidosis." (PMID 30581635, 2018). "GM1 gangliosidosis is an autosomal recessive lysosomal storage disorder due to mutations in the lysosomal acid 3-galactosidase gene, GLB1." (PMID 30581635, 2018). "More recently, injections of adeno‐associated viral vectors (AAV9, AAVrh8) encoding GLB1 have shown success in increasing GLB1 activity, reducing symptoms, and extending lifespan in mice with GM1 gangliosidosis." (PMID 30187681, 2018). "Homozygous mutations in GLB1 gene have been previously reported to be the genetic cause of GM1 gangliosidosis, (OMIM number 203600), which has an autosomal recessive form of inheritance." (PMID 28716012, 2017). "Various forms of GM1-gangliosidosis are caused by GLB1 gene mutations but severity of the disease and age of onset are directly related to the position and the nature of deleterious mutations." (PMID 28716012, 2017). "We subsequently identified compound heterozygous variants in the GLB1 gene, known to cause GM1 gangliosidosis (OMIM 230500) in the affected siblings." (PMID 27679996, 2016). "GM1-gangliosidosis is an inherited autosomal recessive disorder caused by mutations in the gene GLB1, which encodes acid β-galactosidase (β-gal)." (PMID 26958633, 2016). "Mutations in Glb1 are the cause of two human diseases, GM1 gangliosidosis and Morquio disease type B." (PMID 21633714, 2011). "GM1 gangliosidosis (GM1) is an autosomal recessive lysosomal storage disease caused by deficiency of acid beta-galactosidase (GLB1; EC3.2.1.23)." (PMID 20920281, 2010). "In this study, we investigate the GLB1 mutations associated with GM1 gangliosidosis in two Han Chinese patients." (PMID 20920281, 2010). "GM1 gangliosidosis (OMIM 230500) is an LSD caused by genetic defects in the GLB1 gene, which encodes a lysosomal enzyme, β-galactosidase (β-gal), that hydrolyzes the nonreducing terminal β-galactosyl residues of GM1 ganglioside (GM1), glycoproteins, and glycosaminoglycans." (PMID 40198143, 2025). "Defects in GLB1 cause GM1 gangliosidosis where the lipid GM1 accumulates in cells." (PMID 40608809, 2025). "Specific neurodegenerative diseases, such as GM1-gangliosidosis, caused by GLB1 or ceroid lipofuscinosis caused by CLN6 presented a consistent clinical course of early developmental delay followed by neurologic deterioration, seizures, and generalized spasticity." (PMID 37645600, 2023). "β-Galactosidase (GLB1), a lysosomal hydrolytic enzyme, catalyzes the degradation of galactosylceramide to galactose and ceramide within the lysosome and GLB1 mutation causes a deficiency in β-galactosidase-1 resulting in abnormal lysosomal accumulation of GM1 (GM1 gangliosidosis)." (PMID 36504680, 2022). "GM1 gangliosidosis is a rare lysosomal disease caused by the deficiency of the enzyme β-galactosidase (β-Gal; GLB1; E.C. 3.2.1.23), responsible for the hydrolysis of terminal β-galactosyl residues from GM1 ganglioside, glycoproteins, and glycosaminoglycans, such as keratan-sulfate." (PMID 35807262, 2022).